TFF3 (trefoil factor 3)
Description:
Involved in the maintenance and repair of the intestinal mucosa. Promotes the mobility of epithelial cells in healing processes (motogen).
Synonyms: hITF; ITF; TFI; P1B
Tractability: Antibody: UniProt places it where antibodies can reach, with high confidence; its Gene Ontology location is reachable by antibodies, with high confidence; UniProt predicts a signal peptide or a membrane-spanning region.
Gene: Protein-coding gene on chromosome 21 (42,311,667 to 42,315,409, reverse strand). Ensembl gene ENSG00000160180.
Subcellular location: Secreted, extracellular space, extracellular matrix; Cytoplasm
Subcellular location (Human Protein Atlas): Nucleoplasm; Nucleoli; Predicted to be secreted
Pathways (Reactome):
Signal Transduction: Estrogen-dependent gene expression
Gene Ontology:
Molecular function: identical protein binding; protein binding
Biological process: maintenance of gastrointestinal epithelium; regulation of glucose metabolic process
Cellular component: cytoplasm; extracellular region; secretory granule
Genetic constraint (gnomAD): Loss-of-function variants: 6 observed, 9.85 expected, observed/expected ratio (o/e) 0.61, 90% interval 0.33 to 1.2. That is too few expected variants to judge how well the gene tolerates losing a copy. Missense variants: 93 observed, 103.46 expected, observed/expected ratio (o/e) 0.9, 90% interval 0.76 to 1.07. Synonymous variants: 48 observed, 43.24 expected, observed/expected ratio (o/e) 1.11, 90% interval 0.88 to 1.41.
Homologues: Orthologues: chimpanzee TFF3 (99% identical), macaque TFF3 (88% identical), pig TFF3 (81% identical), mouse Tff3 (69% identical), rat Tff3 (68% identical), dog TFF3 (65% identical), tropical clawed frog tff3.8 (36% identical), tropical clawed frog tff3 (35% identical). Paralogues in human: TFF1 (41% identical), TFF2 (40% identical).
Diseases named in the same sentence as TFF3 in open-access papers:
TFF3 is named in the same sentence as 231 diseases in open-access papers, as found by Europe PMC text mining. Sharing a sentence is not in itself a finding about the gene and the disease. The quoted sentences say what the papers report.
colitis (67 papers, 2012 to 2025). Inflammation of the colon. "paracasei L9 on the mucus barrier in DSS-induced colitis mice, Alcian Blue (AB) staining and gene expression quantification of mucin-associated markers (Muc1, Muc2, and Tff3) were performed." (PMID 41515240, 2025). "In the acetic-acid-induced colitis model, dulaglutide enhanced intestinal barrier function, upregulating colonic Trefoil Factor (TFF)-3 expression, as measured by enzyme-linked immunosorbent assay (ELISA)." (PMID 40426955, 2025). "Tff3-deficient mice show markedly increased sensitivity in a dextran sulfate sodium (DSS) colitis model, and these animals are particularly sensitive to radiation-induced mucosal injury and chemotherapy." (PMID 38003531, 2023). "It has been reported that TFF3-deficient mice were more susceptible to DSS-induced colitis, whereas the administration of recombinant TFF3 attenuated DSS-induced colitis." (PMID 35883875, 2022). "After stimulation by dextran sodium sulfate, TFF3-deficient mice were more likely to suffer from colitis." (PMID 34941739, 2021). "Induction of colitis caused a decrease in intestinal Muc2 and TFF3 mRNA levels and an increase in STAT3 mRNA expression as compared to the control group (p < 0.01, p < 0.05, and p < 0.01, respectively)." (PMID 33299531, 2020). "Tff3-deficient (Tff3KO) mice showed strongly increased sensitivity in the dextran sodium sulfate (DSS) colitis model and were particularly sensitive to chemotherapy and radiation-induced mucosal injury." (PMID 31658587, 2019). "In DSS-induced colitis, dietary white and dark kidney beans, as well as dietary cranberry bean supplementation, enhanced the mRNA expression of MUC-2 and Tff3, and mitigated the severity of colitis and associated inflammation." (PMID 28524086, 2017). "TFF3-deficient mice are vulnerable to dextran sulfate sodium-induced colitis, whereas administering TFF3 promotes intestinal barrier function." (PMID 28924192, 2017). "Selective deletion of TFF3, abundantly produced by goblet cells in both the large and small intestine, increases the susceptibility to chemically induced colitis." (PMID 24062746, 2013). "Furthermore, it notably enhanced RELMβ and TFF3 mRNA expression levels, which are key factors associated with goblet cell secretion, in the colon tissue of colitis mice (P < 0.01)." (PMID 39966502, 2025). "Particularly, the levels of TFF peptides (mainly expressed in the gastric glands and goblet cells) are dysregulated in pathological conditions: for instance, TFF3 is up-regulated in gastric ulcers, and tff3−/− mice are more susceptible to colitis after DSS administration." (PMID 37373057, 2023). "Loss of Tff3 was linked to increased dextran sodium sulfate-induced colitis." (PMID 35163705, 2022). "Similarly, Tff3-deficient mice suffer worsened colitis symptoms following exposure to DSS, as well as the increased expansion of the proliferative compartment." (PMID 35334805, 2022). "In patients with UC and experimental colitis models, characterized by a thin mucin layer in association with goblet cell depletion, high expression of Muc1 and Muc4, and low expression of Muc2 and Tff3 have been reported." (PMID 33959000, 2021). "Interestingly, Arhgap17-deficient mice showed increased sensitivity to DSS-induced colitis similar to Tff3 knockout mice." (PMID 27229483, 2016). "Hence, the discovery that VIPKO mice possessed significantly fewer morphologically mature goblet cells, and produced less Muc2 and Tff3 than WT mice offers an additional explanation for their susceptibility to chemically induced colitis." (PMID 25932952, 2015). "Similarly, mice deficient in Tff3 (Tff3-/-) when challenged with DSS developed severe colitis, together with increased IEC apoptosis and poor epithelial regeneration." (PMID 25932952, 2015). "Because the transgene was driven by the Tff3 promoter, we investigate whether Tg mice are less susceptible to chemically induced colitis." (PMID 25974250, 2015).
colitis (continued). "In addition, we revealed that the loss of function of the HIF-1α/TFF-3 axis in DSS-induced colitis in mice may promote intestinal barrier dysfunction." (PMID 32713852, 2020). "In a rat model of colitis, the intestinal administration of TFF3 has demonstrated greater efficacy compared to systemic administration." (PMID 38731435, 2024). "Specifically, EcN adlh colonization led to upregulated the expression of TFF3, a peptide capable of colitis symptoms amelioration." (PMID 39080343, 2024). "Conversely, the subcutaneous injection of TFF3 monomer has been shown to exacerbate colitis induced by mitomycin C or dextran sulfate sodium salt." (PMID 38731435, 2024). "TFF3 serum levels are increased in patients with UC and administration of TFF3 dimer significantly ameliorated the severity of chemically induced colitis in mice." (PMID 39461590, 2024). "In rats with colitis, mucosal expression of TFF‐3 in the distal colon was found to decrease in the acute phase and increase in the healing phase and to play an active role in repairing mucosal damage." (PMID 37776262, 2023). "The expression of TFF3 is downregulated in experimental models of colitis and the damaged tissue of IBD patients, whereas miR-7-5p is overexpressed in IBD samples compared to normal colonic tissue." (PMID 37299399, 2023). "Since TFF3 has a major role in protecting the intestinal barrier, colitis has been found to develop in TFF3 knock‐out mice." (PMID 36748835, 2023). "In this context, we previously showed that EVs from the probiotic EcN were able to counteract the reduced expression of TFF3 in an experimental model of DSS-induced colitis in mice." (PMID 37299399, 2023). "We showed that, in an experimental model of colitis, the oral administration of EVs from the probiotic EcN increased the TFF3 expression in the colonic tissue to levels similar to those of non-colitic mice." (PMID 37299399, 2023). "Emerging evidence indicated that the TFF3 expression profile and biological effects changed significantly in pathological states such as cancer, colitis, gastric ulcer, diabetes mellitus, non-alcoholic fatty liver disease, and nervous system disease." (PMID 35039476, 2022). "Different administration methods for TFF3 dimer significantly ameliorated the severity of colitis induced by dextran sodium sulfate, radiochemotherapy, hypoxia, and trinitrobenzene sulfonic acid." (PMID 35039476, 2022). "In contrast, Tff3 is obviously important for the protection of the host from bacterial infection during the condition of DSS-induced colitis." (PMID 35163705, 2022). "Inhibition of inflammatory response is an important mechanism through which TFF3 ameliorates colitis." (PMID 35039476, 2022). "Tff3-knockout mice are more susceptible to dextran sulfate sodium (DSS)-induced colitis, while oral treatment with TFF3 protected against DSS-induced colitis in mice." (PMID 34002011, 2021). "According to researchers, flavonoids suppressed the activation of TLR-4/NF-κB p65 signaling pathway, leading to a decrease in gene expression of TNF-α, IL-1B, and IL-6, COX-2, TFF-3, and iNOS proteins in the intestinal mucosa in colitis model." (PMID 32848723, 2020). "Of note, in a rat model of DSS-induced colitis, the expression of TFF3 and FCGBP were strongly reduced." (PMID 31658587, 2019). "In a murine model of experimental colitis, oral administration of EcN OMVs counteract the altered expression of pro-inflammatory cytokines and markers of intestinal barrier function such as Trefoil factor-3 (TFF3)." (PMID 31315566, 2019). "The synbiotic FCT (fermented milk with L. gasseri 505 and C. tricuspidata) has demonstrated concurrent upregulation of MUC2, TFF3, and tight junction proteins (occludin, ZO-1), along with significant downregulation of TNF-α, IFN-γ, IL-1β, IL-6, and iNOS/COX-2 in colitis-associated cancer models." (PMID 41395459, 2025).
colitis (continued). "A persistence of cathelicidin in evoking the secretion of TFF3 and RELMβ from goblet cells might eventually deplete mucus stores and exacerbate colitis." (PMID 40735968, 2025). "Interestingly, while I3C treated colitis mice (WT DSS + I3C) increased markers of goblet cells (Tff3 and Clca3b) and cellular proliferation (Mki67), this increased expression was not altered in the AhRΔIEC phenotype." (PMID 38397081, 2024). "Furthermore, intraluminal administration of dimeric TFF3 significantly improved colitis scores in a colitis model." (PMID 35039476, 2022). "Colitis is the first and most concerning disease to be studied using TFF3−/− mice." (PMID 35039476, 2022). "TFF3 is upregulated in the context of inflammatory bowel disease, colitis, and sepsis." (PMID 36069443, 2022). "Loss of TFF3, AGR2 was linked to impaired mucus and increased susceptibility to dextran sodium sulfate-induced colitis., GC Piezo1-/- mice exhibited decreased expression of Mucin2, TFF3, AGR2, and thinner mucus layer, which was consistent with the decreased GC numbers." (PMID 36425784, 2022). "Tail vein administration of 100 nmol/kg of antagomir-7 2 h after TNBS administration and subsequent assessment of the intestinal tissue harvest seven days after treatment revealed improved histological colitis scores, higher TFF3 production, and a reduction in colitis-induced damage." (PMID 34571853, 2021). "Here, we hypothesize that miR-155 contributes to intestinal barrier dysfunction in dextran sulfate sodium (DSS)-induced mice colitis by regulating the HIF-1α/TFF-3 axis." (PMID 32713852, 2020). "In addition, TFF3 also plays an essential role in protecting the mucosal barrier function and protection against the development of colonic inflammation." (PMID 33182355, 2020). "An increase in Muc-2 and TFF3 expression could contribute to protection and enhanced tissue repair in colitis, resulting in improved intestinal histological scores and improved clinical performance observed in these two groups." (PMID 30873029, 2019). "Our data support a model wherein TFF3 produced by goblet cells can bind the LINGO2 extracellular domain (NH2 terminal 350 AA) to de-repress inhibitory LINGO2-EGFR complexes, thereby allowing TFF3 to help maintain mucosal barrier integrity, suppress colitis, and promote immunity against GI helminths." (PMID 31562318, 2019). "We demonstrate that although these diets elevated basal injury scores, they may mitigate colonic injury and epithelial dysfunction induced during colitis by upregulating the proliferation and expression of Tff3, Tgfβ and SCFA transporter expression." (PMID 28346392, 2017). "Previous studies found that Muc2 and Tff3 genes were up-regulated during colitis induction, and suggested that their mRNA levels could be used as early markers of inflammation." (PMID 24416230, 2014). "The lower colonic Muc2 and Tff3 mRNA expressions observed in the DSS-Gln group were consistent with the histological findings that damage to the colonic mucosa was less severe in the colitis group with Gln supplementation." (PMID 24416230, 2014). "Interestingly, exogenous administration of TFF3 was able to reverse colitis, suggesting a potential role of TFF3 in IBD management." (PMID 24062746, 2013). "In fact, Tlr2 has been mostly studied in experimental models of overt colitis where it has been reported that Tlr2 regulates the synthesis of TFF3, a main component of the intestinal mucus, contributing to the protection of the intestinal mucosa and to its restitution after damage." (PMID 22242189, 2012). "However, systemic administration, especially TFF3 monomer, aggravated colitis severity in rats." (PMID 35039476, 2022). "Thus, we also explored the relationship between HIF-1α and TFF-3 in DSS-induced colitis." (PMID 32713852, 2020). "In our study, restoring GLP-1 signaling during colitis in FDD mice significantly up-regulated mucus-related genes (e.g. Muc2 and Tff3), underscoring its role in goblet cell function." (PMID 41202140, 2025).
colitis (continued). "Regarding the therapeutic effect of kaempferol in UC, it was shown to ameliorate colitis in mice via a decrease in plasma Leukotriene B4 (LTB4), nitric oxide and PGE2 levels besides upregulation of TFF3 mRNA level." (PMID 38196993, 2023). "These mice also showed reduced expression of intestinal Tff3, which strongly increased the severity of DSS-induced colitis." (PMID 38003531, 2023). "Indeed, CDX2 is a positive regulator of the Muc2 and Trefoil Factor 3 (TFF3) genes involved in the production and stabilization of the mucus layer, respectively, and whose deficiency induces hypersensitivity to chemically-induced colitis (such as that induced by dextran sulfate sodium (DSS))." (PMID 35203499, 2022). "Previous studies have found that the expression level of TFF3 in colonic mucosa was significantly downregulated in rats with colitis, and mice lacking TFF3 gene displayed significant delayed mucosal healing of colitis." (PMID 38983627, 2024). "It has been reported that Tff3 expression is suppressed in 2,4,6-trinitrobenzenesulfonic acid models of experimental colitis, and the absence of Tff3 expression in DSS induced colitis significantly delays healing of mucosal injury up to 12 d post DSS exposure." (PMID 28346392, 2017). "Thus, OMV-linked factors other than TcpC should contribute to the modulation of mucosal healing markers like TFF-3 and MMP-9, observed in this experimental murine colitis model." (PMID 28744268, 2017). "Moreover, I3C‐treated colitis WT mice showed increased markers of goblet cells (Tff3 and Clca3b); however, this increase was not altered in AhRΔIEC mice." (PMID 40410944, 2025). "Perhaps this is why in the current study there was some discrepancy between in vivo and in vitro colon organoid results in which I3C was able to restore goblet cell markers (Tff3) in vivo after I3C treatment in colitis-induced AhRΔIEC mice, but not AhRΔIEC-derived organoids." (PMID 38397081, 2024). "As illustrated in the heatmap, there were three genes that were significantly downregulated by colitis induction (TNBS + Veh) and restored after disease mice were treated with I3C (TNBS + I3C), which included one mucin protein (Muc2) and two goblet cell markers (Tff1 and Tff3)." (PMID 38397081, 2024). "It has been shown that mice lacking the TFF3 gene are particularly sensitive to DSS-induced mucosal injury, and intestinal epithelial regeneration is severely deficient, leading to massive mortality in mice with colitis." (PMID 39123651, 2024). "Intracolonic injection of TFF3 dimers (but not monomers) ameliorates experimental colitis in rats." (PMID 35039476, 2022). "Furthermore, the present findings also showed that MT supplementation could alleviate LPS-induced colitis and the reduction of goblet cells and MUC2 protein, Villin, and Tff3 mRNA." (PMID 35355860, 2022). "n‐3 polyunsaturated fatty acids attenuate induced colitis by reducing inducible nitric oxide synthase (iNOS), cyclooxygenase‐2 (COX‐2), IL‐6, and LTB4 as well as regulating tight junction proteins (occludin, claudin‐1) and colonic mRNA levels of trefoil factor 3 (TFF3) and mucin 2 (MUC2)." (PMID 32410383, 2020).